HIF1A (hypoxia inducible factor 1 subunit alpha)
Diseases named in the same sentence as HIF1A in open-access papers (continued):
Sharing a sentence is not in itself a finding about the gene and the disease.
cervical carcinoma (continued). "We conducted comprehensive analyses of HIF-1α expression in cervical cancer patients and examined the impact of PX-478 on T cell proliferation, cytokine production, cytotoxicity, and exhaustion markers." (PMID 38425341, 2024). "Numerous studies have unveiled the connection between HIF-1α overexpression and poorer prognosis in cervical cancer patients." (PMID 38425341, 2024). "In cervical cancer progression, both AP-1, hypoxia-inducible factor 1 alpha (HIF1A), and S100A2, which are major mediators of cell response to hypoxia, are associated with the carcinogenesis process." (PMID 38612895, 2024). "In conclusion, our results suggested that JAM3 promotes cervical cancer cell migration and invasion by activating the HIF-1α/VEGFA pathway." (PMID 38760803, 2024). "The overexpression of HOTAIR induces radiation resistance in cervical cancer cells by upregulating HIF-1α expression; however, the mechanism underlying the interaction between HOTAIR and HIF-1α in cervical cancer cells postradiotherapy remains obscure." (PMID 38651153, 2024). "This process leads to the sustained activation of both pathways, highlighting a novel regulatory axis involving HOTAIR and HIF1α in cervical cancer." (PMID 39273054, 2024). "miRNAs are post-transcriptional regulators of gene expression; for example, miR-155 is capable of negatively regulating HIF-1α during prolonged hypoxia, and this miRNA is expressed in cervical cancer, and STAT5 can regulate miR-155 expression." (PMID 38999946, 2024). "In conclusion, PD-1 monoclonal antibodies in tumor-associated macrophages can inhibit the migration and angiogenesis of cervical cancer cells by affecting the PD-1/IRE1α/SHP2/HIF1α signaling pathway, thereby inhibiting the progression of cervical cancer." (PMID 39207449, 2024). "Our results suggest a new model in which HOTAIR sustains reciprocal activation of the PI3K/AKT and Wnt/β-catenin pathways through the HOTAIR/HIF1α axis, thereby contributing to the oncogenic phenotype of cervical cancer." (PMID 39273054, 2024). "The following studies provide a brief summary of how hypoxia regulates HIF1α transcription, propofol enhances paclitaxel-induced cervical cancer cell ferroptosis." (PMID 38536579, 2024). "We found that PD-1 monoclonal antibodies can influence the expression of the PD-1/IRE1α/SHP2/HIF1α signaling pathway in TAMs and inhibit the migration and neovascularization of cervical cancer cells." (PMID 39207449, 2024). "Under hypoxia (1% O2), HIF-1α upregulates miR-147a expression and inhibits the proliferation of cervical cancer HeLa cells, indicating that HIF-1α regulates cell growth." (PMID 38766303, 2024). "To elaborate, knocking E6 out considerably decreases HIF-1a’s levels, a change that, in combination with PD-L1’s decrease in the E6KO cell lines, implicates that PD-L1’s upregulation in HPV16-caused cervical cancer happens in a HIF-1a related manner." (PMID 38257813, 2024). "Our in-silico analyses revealed high expression of HIF-1α in cervical cancer patients, correlating with poor prognosis." (PMID 38425341, 2024). "Our findings underscore the clinical relevance of HIF-1α overexpression in cervical cancer patients and highlight the potential challenges in targeting HIF-1α for enhancing CAR T cell therapy efficacy." (PMID 38425341, 2024). "Aberrant expression of HOTAIR strongly induced HIF-1α expression in cervical cancer cells and in mice models exposed to radiation." (PMID 38887279, 2024). "In summary, our study demonstrates the significant impact of HIF-1α inhibition using the PX-478 inhibitor on mesoCAR T cell function within the cervical cancer microenvironment." (PMID 38425341, 2024). "In order to evaluate the internal mechanism that FDG uptake was closely related to the expression of PD-L1, we performed HIF1α staining and quantitative analysis on cervical cancer sections." (PMID 36980323, 2023).
cervical carcinoma (continued). "In cervical cancer, both in vitro and in vivo studies have shown that SOX12-induced SNHG15 promotes cervical cancer tumorigenesis and resistance to cisplatin via the miR-4735-3p/HIF1a pathway." (PMID 37056344, 2023). "Pre-chemotherapy cervical cancer biopsies showed strong positive staining of HIF-1α, VEGF-A, and Ki67, while weak or moderate positive staining was seen in post-chemotherapy specimens." (PMID 37335690, 2023). "Subjecting cervical cancer cell lines to hypoxia increased the levels of HIF-1α and PLOD2, and the migration and invasion of cells mediated by PLOD2 were dependent on HIF-1α." (PMID 35625561, 2022). "In the first two parts of this study, we confirmed the role of HIF-1α in the progression, invasion, and metastasis of cervical cancer from the tissue and cellular levels." (PMID 35664561, 2022). "Further, hTid-1 has been found to interact with the von Hippel-Lindau protein to destabilize Hypoxia Inducible Factor 1-alpha (HIF-1α) in sarcoma and cervical cancer cells, thereby regulating angiogenesis." (PMID 35854300, 2022). "miR-200 promotes the proliferation of cervical cancer cells by regulating the HIF-1α/VEGF signaling pathway." (PMID 35795276, 2022). "LncRNA HITT can reduce HIF1α protein translation through YBX1 in colorectal tumors and cervical cancer while forming a feedback regulatory loop with HIF1α to regulate angiogenesis and tumor growth." (PMID 35692750, 2022). "In conclusion, HIF-1α significantly promotes the proliferation, invasion, and migration of cervical carcinoma cells by upregulating YAP/TAZ." (PMID 35664561, 2022). "For example, overexpression of HOTAIR increases cellular radioresistivity through the modulation of WIF-1, HIF-1α, and p21 in pancreatic ductal adenocarcinoma cells, cervical cancer cell lines, and HeLa and C33A cells, respectively." (PMID 36457703, 2022). "Further mechanistic studies showed that HOTAIR regulates the radiosensitivity of cervical cancer cells and is related to HIF-1α expression." (PMID 35692795, 2022). "SOX12 enhances the Tumorigenic Properties and Chemoresistance in Cervical Cancer by targeting lncRNA SNHG15/miR-4735-3p/HIF1a Pathway." (PMID 35485164, 2022). "SNHG15 is upregulated in cervical cancer tissues and promotes cervical cancer progression via the miR-4735-3p/HIF1a axis." (PMID 35406713, 2022). "The expression level of HIF-1α in cervical cancer tissue was higher than CIN and normal cervical tissue." (PMID 35664561, 2022). "For instance, hypoxic TME enhanced radioresistance of cervical cancer cells by upregulating hypoxia-inducible factor 1α (HIF-1α) expression." (PMID 36313645, 2022). "As a key gene in the feedback regulatory loop, HIF-1α affects the sensitivity of cervical cancer cells to chemotherapy." (PMID 35795276, 2022). "In contrast, knockdown of HOTAIR increased the radiosensitivity of cervical cancer cells by increasing the expression of miR-217 and decreasing the expression of HIF-1α." (PMID 35692795, 2022). "Several hypoxia-related genes have been identified as robust biomarkers in predicting overall survival (OS) of patients with cervical cancer, such as hypoxia-inducible factor-1 alpha (HIF-1α)." (PMID 35657977, 2022). "All in all, the results in the present study suggest that hypoxia induced OIP5-AS1 promotes the Warburg effect through miR-124-5p/IDH2/HIF-1α pathway in cervical cancer." (PMID 34513821, 2021). "Taken together, the present study indicates that the high expression of OIP5-AS1 promoted the Warburg effect through miR-124-5p/IDH2/HIF-1α pathway in cervical cancer, and is a potential cervical cancer treatment target." (PMID 34513821, 2021). "Boosting lipid catabolism by ATGL over-expression has a pro-tumor role in cervical cancer cells, dependent on ROS production and HIF1α induction." (PMID 33706793, 2021). "We also performed ICC analysis of HIF‐1α in other kinds of cultured cells, such as HeLa cervical cancer cells." (PMID 33369883, 2021).
cervical carcinoma (continued). "Whilst HSF4 transcriptionally activated HIF1a expression in HCC cells, HSF4 was reported to co-opt with HSF2 to repress HIF1a expression and subsequently inhibit the expression of HIF1a downstream target genes in breast and cervical cancer cells." (PMID 33807297, 2021). "For this reason, the link here described between ATGL and HIF1α signaling mediated by ROS exposes a potential intervention point aimed to restrain cell resistance of cervical cancer cells." (PMID 33706793, 2021). "Among the transcription factors activating BNIP3 expression the most characterized is HIF1α, which attracted our attention because it is also known for promoting glycolysis and proliferation of cervical cancer cells." (PMID 33706793, 2021). "In conclusion, hypoxia induced OIP5-AS1 promotes the Warburg effect through miR-124-5p/IDH2/HIF-1α pathway in cervical cancer." (PMID 34513821, 2021). "In particular, HOTAIR, an oncogenic lncRNA overexpressed in human cervical cancer HeLa and C33A cells, rendered them radioresistant via the upregulation of HIF-1α expression." (PMID 33806538, 2021). "More research should be done to investigate the role of HIF1-α in activating survival pathways following taxane treatment in cervical cancer." (PMID 33182737, 2020). "Lately, Ube2s was found to have a positive correlation with HIF-1α signaling in renal and cervical cancer cells." (PMID 32250966, 2020). "Overexpression of HIF-1α has been reported to be a marker of poor prognosis in patients with cervical cancer." (PMID 33135539, 2020). "There is limited evidence supporting a possible relationship between the autophagy pathway and HIF1-α in taxane-resistant cervical cancer." (PMID 33182737, 2020). "EGFR activation induces translocation of PKM2 into the nucleus, where PKM2 acts both as a protein kinase and a transcriptional coactivator for hypoxia-inducible factor alpha (HIF-1α) in HeLa cervical carcinoma cells." (PMID 32695675, 2020). "The expression levels of Col1A1, Col3A1, Col4A1 and HIF-1α were positively correlated with P4HA2 levels in TCGA cervical cancer cohort (P < 0.001)." (PMID 32226497, 2020). "Radiotherapy inhibits cervical cancer cell growth through downregulating HOTAIR to inhibit the expression of HIF-1α." (PMID 32963532, 2020). "In this study, we demonstrate the association between PI, RI, HIF-1α and the clinical response after external radiation in patients with stage IIB to IVA cervical cancer." (PMID 31350968, 2019). "Our study suggests that PI and HIF-1α expression can predict the clinical response after radiation in patients with cervical cancer." (PMID 31350968, 2019). "This study is aimed to evaluate the ability of pulsatility index (PI), resistance index (RI), and hypoxia inducible factor-1α (HIF-1α) expression in predicting the clinical response after radiation in patients with cervical cancer." (PMID 31350968, 2019). "PI and HIF-1α expression predict the clinical response after radiation in patients with cervical cancer." (PMID 31350968, 2019). "To this end, we demonstrate that NF90 is upregulated in cervical cancer specimens, mediates the upregulation of HIF-1α/VEGF-A, as well as the endothelial tube formation through PI3K/Akt signaling pathway." (PMID 29449553, 2018). "In this study, we investigated the expression of HOTAIR in cervical cancer cells exposed to radiotherapy and analyzed the impact of HOTAIR and HIF-1α on the radiotherapy effect in cervical cancer cells." (PMID 30355300, 2018).
cervical carcinoma (continued). "In the current study, we found that HOTAIR overexpression induced the radioresistance through upregulating the expression of HIF-1α in cervical cancer cells." (PMID 30355300, 2018). "In the present study, we aimed to evaluate the potential involvement of NF90 in the expression of HIF-1α/VEGF-A in cervical cancer cells and regulation of angiogenesis." (PMID 29449553, 2018). "Compared with normal tissue, HOTAIR expression level increased 2.2 fold (p = 0.0045) in cervical cancer tissue, and HIF-1α expression was also upregulated in cervical cancer tissue." (PMID 30355300, 2018). "In invasive cervical carcinomas, Trx upregulation was detected in tumor microregions suffering from hypoxia, suggesting hypoxia-inducible factor-1 α (HIF-1α) induction, which is entailed by PI3K/AKT pathway activation." (PMID 30248944, 2018). "In the study of cervical cancer, HIF-1α overexpression was also proved to predict early-stage tumor invasion and unfavorable prognosis." (PMID 29899167, 2018). "We show that STS-induced Twist1 expression is mediated in a HIF-1α–dependent manner in human prostate and cervical cancer cells." (PMID 28977889, 2017). "In cervical cancer, the high expression of HIF-1α leads to increased VEGF expression and angiogenesis." (PMID 28592805, 2017). "High levels of mTOR, HIF-1α, c-Myc, and PKM2 were associated with a positive chemotherapy response in cervical cancer patients treated with cisplatin-based NACT." (PMID 27492148, 2016). "Pre-chemotherapy cervical cancer tissues consistently showed moderate or intense positive staining of mTOR, HIF-1α, c-Myc, and PKM2, while post-chemotherapy tissue consistently showed weak or moderate positive staining." (PMID 27492148, 2016). "Our study identified four cell metabolism associated proteins, mTOR, HIF-1α, c-Myc, and PKM2, as potential biomarkers to predict the response to cisplatin in cervical cancer patients." (PMID 27492148, 2016). "In the present study, our data provides evidence that high expression of HIF-1α was significantly correlated with a positive response to chemotherapy in cervical cancer." (PMID 27492148, 2016). "We found that the mTOR/HIF-1α/c-Myc/PKM2 signaling pathway was significantly downregulated in post-chemotherapy cervical cancer tissues." (PMID 27492148, 2016). "In vitro and in vivo data showed that bortezomib protected HIF-1α from proteasome degradation and impaired its function in cervical cancer." (PMID 26416246, 2015). "We demonstrate that c-Met correlates with HIF-1α and is prognostic factor in survival in cervical cancer." (PMID 23927384, 2013). "In those markers, HIF-1α and c-Met were associated with LN metastasis and FIGO stage in cervical cancer." (PMID 23927384, 2013). "We demonstrate that c-Met correlates with HIF-1α and is a poor prognostic factor in survival in cervical cancer." (PMID 23927384, 2013). "In our knowledge, this is the first report of correlation between HIF-1α and c-Met in cervical cancer tissue." (PMID 23927384, 2013). "The reduced expression of HIF-1α in perinecrotic regions (border between necrosis and hypoxia) has been observed in various human tumors and in xenografts of SiHa cervical carcinoma, WiDr colon carcinoma, and M006 astrocytoma." (PMID 23203043, 2012). "Transient transfection of E6 and E7 expression vectors into cervical cancer cell lines was reported to induce higher HIF-1α levels under normoxic conditions." (PMID 22032288, 2011). "We investigated the mechanism of TPZ on HIF-1α in HeLa human cervical cancer cells by western blot analysis, reverse transcription-PCR assay, luciferase reporter assay and small interfering RNA (siRNA) assay." (PMID 21085474, 2010).
cervical carcinoma (continued). "In this study, we used human cervical-cancer (HeLa) cells to characterize and investigate the mechanisms involved in the reduction of HIF-1α protein levels by TPZ." (PMID 21085474, 2010). "In cervical cancer, circCCDC134, circ_0004543, and circ-HIPK3 all upregulate the expression of HIF-1α by acting as miRNA sponges, thus promoting the proliferation, migration, and invasion of cervical cancer cells and thereby accelerating tumor growth and metastasis." (PMID 40004471, 2025). "Similarly, HIF1A was one of the core targets and enriched pathways of the aqueous extract of Solanecio mannii roots in exerting its therapeutic activity against cervical cancer." (PMID 40446016, 2025). "Our study corroborates these findings by revealing the downregulation of immune-related hub genes such as HSPA90AA1, CTNNB1, and HIF1A in HPV-positive cervical cancer, which could impair immune cell infiltration and contribute to immune escape." (PMID 41465546, 2025). "Our research strongly supports the existing data, given that HIF-1a mRNA levels appear significantly increased in the cervical cancer cell lines when compared to the normal cervical keratinocytes, and correlates E6’s presence in the cancer cells with HIF-1a’s expression increase." (PMID 38257813, 2024). "Our data unequivocally demonstrate an upregulation of HIF-1α in cervical cancer patients." (PMID 38425341, 2024). "Previous studies have shown that circCCDC134 enhanced its stability and promoted HIF1A transcription by m6A modification, thereby promoting cervical cancer growth and metastasis by serving as a recruitment p65 in the nucleus and a miR-503-5p sponge regulating MYB expression in the cytoplasm." (PMID 38778089, 2024). "Our data could propose a molecular network that leads to PD-L1’s upregulation in HPV16 related cervical cancer through a mir-143/HIF-1a mediated axis and, consequently, to cervical cancer’s ability to escape immunosurveillance." (PMID 38257813, 2024). "Undertaking this endeavor, we are committed to understanding the mechanism behind this interaction, with the exploration of a network or a possible molecular pathway that includes HPV16 E6, a miRNA, HIF-1a and PD-L1 that probably promotes cervical cancer’s immune evasion." (PMID 38257813, 2024). "Elevated HIF-1α expression preradiotherapy has been proposed as being a predictive biomarker for suboptimal response to preoperative radiotherapy in patients with laryngeal, oropharyngeal, laryngeal, esophageal, and cervical cancer." (PMID 38651153, 2024). "Therefore, there is a HIF-1α-miRNAs − 21 positive feedback loop through the PTEN/Akt/HIF-1α pathway in cervical cancer cells." (PMID 38965615, 2024). "Likewise, our results indicate that miR-143 is in an interplay with the expression of PD-L1 in cervical cancer cells, yet this interaction possibly happens in an indirect way, via the HIF-1a inhibition." (PMID 38257813, 2024). "Interestingly, recent studies have found that HDAC4 regulates the lysine acetylation of HIF1α protein and enhances HIF1α stability in cervical cancer." (PMID 37149664, 2023). "Additionally, the effect of M4N on intracellular contents of HIF1A under hypoxic conditions was examined in cultured human Hela cervical cancer cells." (PMID 37228120, 2023). "Additionally, boosting lipid catabolism, which has a pro-tumoral effect, is dependent on ROS production and HIF1α induction in cervical cancer cells." (PMID 37762214, 2023). "We speculate that HIF-1α gene silencing inhibits the growth and metastasis of cervical cancer cells through a variety of ways and may become a potential effective target for cervical cancer gene therapy." (PMID 35664561, 2022). "On the contrary, overexpression of HIF-1α increased the expression of YAP/TAZ, and the invasion, migration, and proliferation of cervical cancer cells were enhanced, suggesting that HIF-1α regulates the development of cervical cancer by regulating the YAP/TAZ target." (PMID 35664561, 2022).